MDM2 (MDM2 proto-oncogene)
Diseases named in the same sentence as MDM2 in open-access papers (continued):
Sharing a sentence is not in itself a finding about the gene and the disease.
tumor (continued). "The tumor cells show diffuse strong expression of Factor VIII, Fli-1, INI-1, vimentin, MDM2, and CDK4, local expression of CD31, AE1/AE3, EMA and P63, and no expression of CD34, S-100, actin-sm, desmin, MyoD1, and HMB45." (PMID 26315812, 2015). "In contrast, mutations and CN alterations affecting cell cycle regulators, such as MYCN, CDK4 and CDKN2A/B, except for MDM2, were particularly enriched in the A1/A2 clusters compared with the E1/E2 clusters (P=0.016), suggesting that these genes may have driver roles in A1/A2 tumours." (PMID 26138366, 2015). "SNP array identified frequent shared copy number events in all three tumor regions including FGFR1 amplification at chromosome 8p11.23 and classical CDK4, HMGA2 and MDM2 amplification at chromosome 12q13-15 region and deletion of TP53BP1 at chromosome 15q15." (PMID 26643872, 2015). "In every tumor that exhibited EGFR, PDGFRA, NTRK1, MDM2, MDM4, or CDK4 amplification, the increased copy number was contained within, or contained translocations into, a suspect chromothriptic region." (PMID 26328271, 2015). "Analysis of The Cancer Genome Atlas (TCGA) data set shows that in UC, 10 out of 11 MDM2-amplified tumours are also FRS2-amplified and NanoString analysis confirmed high FRS2 expression in our patient’s tumour sample." (PMID 26497743, 2015). "Other alterations such as amplifications of PDGFRA, MDM2 and MDM4 were also identified as important events occurring at different steps of tumor expansion depending on the patient." (PMID 25940437, 2015). "But in combination, MDM2 plus BRAF inhibition and MDM2 plus MEK inhibition elicited 89 and 93% decreases in tumor volume, respectively (p < 0.0001 for each combination vs. its respective single-agent comparators)." (PMID 24810962, 2014).
tumor (continued). "Interestingly, a number of genes that change their expression in immortalized cells, e.g. PI3K, MDM2, SMAD2/3 and STAT1, are implicated in the evasion of apoptosis and acquisition of insensitivity to growth-inhibiting signals, which are characteristic features of tumour cells." (PMID 24371281, 2014). "Note that treatment with the MDM2 inhibitor, Nutlin-3, significantly reduces DNMT3A and DNMT3B expression and methylation of TSGs, as well as tumor growth in vivo." (PMID 25949795, 2014). "MDM2, MEK and BRAF inhibitor monotherapy conferred tumor volume reductions of 24, 51 and 23%, respectively." (PMID 24810962, 2014). "In this region, there are important oncogenes such as CHOP (DDIT3), GLI, MDM2, CDK4, SAS, HMGA2, but also the HOXC locus, involved in development and tumor progression." (PMID 24085196, 2013). "The expression data revealed an increased (≥3-fold) expression of transcriptional regulators in HCC-R tumor tissues (MYC (3.72), CTNNB1 (3.19), and MDM2 (4.27))." (PMID 24377043, 2013). "The majority of MDM2 SNP309 (36/41 (88%)) and MDM4 SNP7 (39/43 (91%)) genotypes were identical between the tumor and germline samples." (PMID 22916154, 2012). "The genomic region spanning MDM2 SNP309 and MDM4 SNP7 were PCR amplified and sequenced from both germline and tumor DNA samples." (PMID 22916154, 2012). "Thus, Mdm2 with appropriate levels may act as a tumor suppressor." (PMID 22679490, 2012). "Ectopic expression of PRDM5 inhibited tumor cell clonogenicity, at least partially through antagonizing WNT/β-catenin signaling and oncogene expression such as CDK4, TWIST1, and MDM2." (PMID 22087297, 2011).
tumor (continued). "The level of SIRT1 was low, while high amounts of BCL2, MDM2 and PTBP1 were noted in both types of tumours." (PMID 21655185, 2011). "In our patient, IHC and FISH analyses for MDM2 and CDK4 were done on 2006 from paraffin-embedded tumour samples biopsied on 2004." (PMID 21106072, 2010). "Therefore, the aim of the presented study was the analysis of the allele frequencies of the Mdm2 SNP309 in patients with PCa compared to a healthy control group to assess a possible influence of this promoter alteration on cancer risk, histopathological tumour characteristics and prognosis." (PMID 18577987, 2008). "In females, the MDM2 SNP309 locus and the age of tumor diagnosis share significant mutual information whereas, in males, the level of mutual information measured did not quite reach significance." (PMID 18398474, 2008). "Specifically, in female carriers, the MDM2 SNP309 locus and the age of tumor diagnosis share a significant 0.2 bits of mutual information (p = 0.014)." (PMID 18398474, 2008). "Recently, the tumour suppressor P14ARF was shown to influence MDM2 function by binding and transporting MDM2 into the nucleolus for inactivation." (PMID 11953887, 2002). "Interestingly, 20q13 and MDM2 amplifications showed some degree of correlation to each other, which may possibly be owing to the fact that both events occurred preferentially in aneuploid tumours." (PMID 8980401, 1996). "In parallel, we had also tested our tumour DNAs for amplification of CCND1, ERBB-2 and MYC, which made it possible to test for correlations with 20q13 or MDM2 amplifications." (PMID 8980401, 1996). "Within the MDM compartment, subtypes MDM1 and MDM2 were consistently enriched in tumor regions relative to non-malignant tissue." (PMID 41503214, 2026). "Additionally, MDM2 interacts with STAT5, preventing its degradation and stabilizing its expression in tumor-infiltrating T cells, further contributing to tumor progression." (PMID 41170373, 2025).
tumor (continued). "By comparing the cfDNA WGS with sequencing on the primary tumor and metastasis at the time of relapse, we demonstrated a high degree of concordance in the identification of key genomic alterations, including MYCN and CDK4/MDM2 amplifications." (PMID 40386554, 2025). "We also observed a correlation between the MDM2 methylation and the gender, AFP, number of tumors, tumor size, vascular invasion and TNM stage, which means MDM2 methylation might take part in the development of HBV-related HCC." (PMID 40432974, 2025). "The tumor exhibits positivity for Vimentin, PR, and SMA, with negativity for PanCk, S100, Desmin, PSA, CK5/6, BCL2, MDM2, and Melan A. Additionally, the Ki-67 proliferation index is approximately 25 %, and CD34 highlights only the vascular walls without tumor cell positivity." (PMID 40686513, 2025). "Notably, IDH1 R132Q-expressing U87MG tumor xenografts had significantly increased transcripts of many integrins as described, as well as EGFR and MDM2 compared to R132H." (PMID 40188944, 2025). "No adjacent atypical lipogenic tumor component was present; however, MDM2 FISH was not performed on that component for clarification." (PMID 40211332, 2025). "Unlike in the navtemadlin-treated tumor cell proteome, we did not detect MDM2 or p21 in the navtemadlin-treated endothelial proteome by mass spectrometry; the proteins were, however, detected by western analysis." (PMID 41360924, 2025). "Fluorescence in situ hybridization (FISH) analysis indicated a hemizygous deletion of the RB1 locus in 36% of tumor cells, with no MDM2 amplification detected." (PMID 41230282, 2025). "Another interesting speculation involves Tumor Microenvironment (TME) and the mechanisms of MDM2 in various types of immune cells." (PMID 41515979, 2025). "A fluorescence in situ hybridization study indicated no amplification of the MDM2 gene in the tumor cells, and the MDM2 signal index/CEN12 was 1.1." (PMID 40710010, 2025). "There is evidence that MDM2 ubiquitinates and degrades SIRT6, a significant tumor suppressor." (PMID 40308267, 2025). "Furthermore, amplification or overexpression of the MDM2 (Murine Double Minute 2) and CDK4 genes has been observed in OS, suggesting their involvement in tumor development." (PMID 40076599, 2025). "The interaction of SPAG5 with key hub genes such as MDM2 and CDK1 not only reinforces its role in tumour suppression through negative regulation but also highlights its potential in moderating the phenotypic and genomic alterations associated with AML progression." (PMID 39762615, 2025).
tumor (continued). "The naked MDM2-siRNA and scramble-siRNA complex had little effect on the tumor growth and survival time, suggesting that the observed tumor-growth inhibition by the MDM2-siRNA complex was due to silencing of MDM2 mRNA, not to an off-target effect." (PMID 41009451, 2025). "Strikingly, a mixed control group of 12 benign and malignant PLAG1-altered neoplasms showed no immunohistochemical staining for MDM2." (PMID 40338436, 2025). "The comparison of the tumor proteomes with and without MDM2 amplification revealed 48 differentially expressed proteins." (PMID 41299419, 2025). "The absence of P14arf can result in an increase in the noncompetitive activity of MDM2, thereby promoting tumor cell proliferation and conferring enhanced resistance to immunotherapy." (PMID 39281319, 2024). "Interestingly, another MDM2 inhibitor, APG-115, has a unique role in enhancing anti-tumor immunity, offering hope for patients resistant to immunotherapy." (PMID 39223632, 2024). "Previous research has shown that MDM2 protein, whether expressed in tumor cells or CD4 + T cells, negatively regulates tumor-infiltrating CD4 + T cells and contributes to immune evasion." (PMID 38281981, 2024). "In addition, the tumor suppressor PTEN inhibits the PI3K/AKT signaling pathway, while AKT promotes transcription of MDM2 gene, and the entry of MDM2 protein into the nucleus and phosphorylation." (PMID 38741108, 2024). "In contrast, TAM (tumor‐associated macrophage) C16 was enriched in lung tumors and highly expressed PDE4B but not IL1B, MDM2, or PELI1." (PMID 38010945, 2024). "Statistically significant differences were observed between the cohorts in MDM2 amplification status, final histology, tumor depth, tumor location, mean tumor 2D axial diameter and tumor volume of MDM2 negative tumors (P < 0.05)." (PMID 39351025, 2024). "Thus, the 14-3-3σ/MDM2 PPI is also a potential therapeutic target for drug molecules that would stabilize the interaction and promote tumor suppression." (PMID 38237679, 2024).